CBLN4 (cerebellin 4 precursor)
Description:
Acts as a synaptic organizer in specific subsets of neurons in the brain (By similarity). Essential for the formation and maintenance of inhibitory GABAergic synapses (By similarity). Promotes the development of dendrite-targeting inhibitory GABAergic synapses made by somatostatin-positive interneurons (By similarity). May contribute to the function of ventral medial habenula region of the brain implicated in the regulation of anxiety-related behaviors (By similarity). May play a role in CBLN3 export from the endoplasmic reticulum and secretion (By similarity).
Synonyms: CBLNL1; dJ885A10.1
Tractability: Antibody: UniProt places it where antibodies can reach, with medium confidence; UniProt predicts a signal peptide or a membrane-spanning region; its Gene Ontology location is reachable by antibodies, with medium confidence.
Gene: Protein-coding gene on chromosome 20 (55,997,357 to 56,005,519, reverse strand). Ensembl gene ENSG00000054803.
Subcellular location: Secreted; Synapse
Subcellular location (Human Protein Atlas): Cytosol; Flagellar centriole; Mid piece; Principal piece; Calyx; Perinuclear theca; Predicted to be secreted
Gene Ontology:
Biological process: inhibitory synapse assembly; maintenance of synapse structure; trans-synaptic signaling, modulating synaptic transmission; trans-synaptic signaling by trans-synaptic complex, modulating synaptic transmission
Cellular component: extracellular matrix; extracellular region; GABA-ergic synapse; synapse; synaptic cleft; glutamatergic synapse
Genetic constraint (gnomAD): Loss-of-function variants: 4 observed, 9.63 expected, observed/expected ratio (o/e) 0.42, 90% interval 0.2 to 0.95. That is too few expected variants to judge how well the gene tolerates losing a copy. Missense variants: 158 observed, 214.93 expected, observed/expected ratio (o/e) 0.74, 90% interval 0.64 to 0.84. Synonymous variants: 108 observed, 98.1 expected, observed/expected ratio (o/e) 1.1, 90% interval 0.94 to 1.29.
Homologues: Orthologues: chimpanzee CBLN4 (100% identical), macaque CBLN4 (99% identical), guinea pig CBLN4 (99% identical), pig CBLN4 (99% identical), rabbit CBLN4 (98% identical), rat Cbln4 (97% identical), mouse Cbln4 (96% identical), dog CBLN4 (90% identical), tropical clawed frog cbln4 (90% identical), zebrafish cbln4 (83% identical). Paralogues in human: CBLN2 (70% identical), CBLN1 (66% identical), CBLN3 (54% identical).
Diseases named in the same sentence as CBLN4 in open-access papers:
CBLN4 is named in the same sentence as 16 diseases in open-access papers, as found by Europe PMC text mining. Sharing a sentence is not in itself a finding about the gene and the disease. The quoted sentences say what the papers report.
Alzheimer disease (3 papers, 2019 to 2022). A progressive, neurodegenerative disease characterized by loss of function and death of nerve cells in several areas of the brain leading to loss of cognitive function such as memory and language. "For example, RBM8A is an RNA binding protein that has differential expression in Alzheimer's disease, and DNA methylation on RHBDF 2 gene may have a role in the onset of AD, the increase of CBLN4 may be a potential therapy for AD." (PMID 31816601, 2019).
autism (3 papers, 2022 to 2023). Persistent deficits in social interaction and communication and interaction as well as a markedly restricted repertoire of activity and interest as well as repetitive patterns of behavior. "MG was also associated with SNPs in the brain- and neuron-specific genes, including cerebellum 4 precursor (CBLN4), potassium channel KCNH5, adenylate cyclase 8 (ADCY8), and autism susceptibility candidate gene AUTS2." (PMID 35711735, 2022).
amyloid (1 paper, 2025). "Meanwhile, CBLN4, pivotal for synaptic formation and maintenance, has been suggested as a treatment target of AD due to its amelioration of amyloid‐related synaptic dysfunction." (PMID 40110647, 2025).
brain tumors (1 paper, 2020). "The results of the MS‐HRM analysis of all analyzed genes (SFRP1, SFRP2, RUNX3, CBLN4, INA, MGMT, and RASSF1A) showed that their promoter sequence methylation level is significantly higher (P < 0.0001) in DNA samples from brain tumor patients than in the non‐neoplastic brain sample." (PMID 32783304, 2020).
colorectal cancer (1 paper, 2019). A primary or metastatic malignant neoplasm that affects the colon or rectum. "CBLN4 binds strongly to presynaptic deleted in colorectal cancer (DDC), a transmembrane receptor that has a well‐established role in axon guidance." (PMID 31374129, 2019).
glioma (1 paper, 2020). A benign or malignant brain and spinal cord tumor that arises from glial cells (astrocytes, oligodendrocytes, ependymal cells). "Forty‐six glioma samples and one non‐neoplastic brain sample were analyzed by MS‐HRM in terms of SFRP1, SFRP2, RUNX3, CBLN4, INA, MGMT, and RASSF1A promoter methylation." (PMID 32783304, 2020).
CBLN4 also shares sentences with these, for which no sentence is quoted: psychiatric disorder (3 papers); attention deficit-hyperactivity disorder (1); brain glioma (1); cancer (1); cannabis dependence (1); dementia (1); infection (1); Intellectual disability (1); Parkinson disease (1); schizophrenia (1).